TDO2 (tryptophan 2,3-dioxygenase)
Diseases named in the same sentence as TDO2 in open-access papers (continued):
Sharing a sentence is not in itself a finding about the gene and the disease.
tumor (continued). "In our recent preclinical studies, dual inhibition of IDO1 and TDO2 with the novel agent AT-0174 effectively reduced KYN levels, increased tumor infiltration with natural killer cells, and reduced regulatory T cells in cisplatin-resistant lung cancer models." (PMID 39911818, 2024). "The results revealed that in comparison with the normal tissues, tumor tissues from ccRCC patients exhibited obviously high CYP1B1, KMO, and TDO2 staining." (PMID 38183155, 2024). "They found TDO2 downregulated in HCC tissues and its expression negatively correlated with tumor size, clinical stage, TNM stage, and tumor differentiation." (PMID 38462620, 2024). "The dual IDO1/TDO2 inhibitor, STS, effectively boosts the anti-tumor effects of the PD1 antibody in CRC." (PMID 38462620, 2024). "Increased IDO1 and TDO2 activity is known to suppress the cytotoxic T cell response to tumour cells, and this has led to the proposal that the IDO1 and TDO2 enzymes represent promising immuno-oncology targets." (PMID 39048947, 2024). "Protein expression predominantly clustered within high-density tumor cell regions, notably with AhR and IDO2 demonstrating markedly elevated levels compared to IDO1 and TDO2." (PMID 38951170, 2024). "We evaluated the effect of administering the orally bioavailable IDO1/TDO2 inhibitor AT-0174 alone and in combination with an anti-PD1 antibody on tumor growth and survival." (PMID 37226257, 2023). "We evaluated the IHC staining of Trp‐catabolizing enzymes, including IDO1, IDO2, TDO2, and IL4I1, in tumor cells." (PMID 37148546, 2023). "Surprisingly, although Ido1, Ido2 and Tdo2 were barely expressed in MEPs, a high level of Kyn was found in the MEPs of tumor-bearing mice and a very low Kyn level was present in the MEPs of tumor-free mice, suggesting that MEPs from tumor-bearing hosts might use exogenous Kyn to activate AhR." (PMID 37919525, 2023). "Significantly lower tumor weights were found in all of the treatment groups, with IDO1/TDO2 inhibition plus PD1 blockade yielding the greatest reductions." (PMID 37226257, 2023). "The degradation of Tryptophan to Kynurenine is catabolized by tryptophan enzymes, including IDO1, IDO2, TDO2, and IL4I1, which up‐regulate PD‐L1 expression and promote tumor suppressive microenvironment in various cancers." (PMID 37148546, 2023). "Clinical samples showed significant downregulation of the following genes: CPT2, ACAA2, HPGD and ALDH3A2, while the expression of ENO2, TDO2, CPOX, ACADL and PTPRG was significantly upregulated in the tumor tissue (p < 0.01)." (PMID 36230866, 2022). "We revealed that TDO2 expression was upregulated in RCC tissues and correlated with tumor grade, metastatic status, stage, and histologic grade." (PMID 34174844, 2021). "Tryptophan metabolism of T-cell is mediated by tumor cells through high expression of indoleamine 2,3-dioxygenase (IDO) and tryptophan-2,3-dioxygenase (TDO), which can convert tryptophan into kynurenine and its metabolites." (PMID 32850400, 2020). "Within tumor cells, indoleamine-2,3-dioxygenase (IDO) and tryptophan-2,3-dioxygenase (TDO)-mediated tryptophan catabolism produces the active metabolite kynurenine, an agonist of the aryl hydrocarbon receptor (AhR) that exerts immunosuppressive functions." (PMID 32483452, 2020). "Kynurenine is synthesized during tryptophan catabolism by indoleamine 2,3-dioxygenase (IDO) or tryptophan 2,3-dioxygenase (TDO), and has been shown to suppress anti-tumor immune responses." (PMID 31554815, 2019). "Univariate analysis of clinical specimens revealed that a longer overall survival is achieved in the group with lower expression of tryptophan 2,3-dioxygenase 2 (TDO2) and AHR in cells surrounding the tumor." (PMID 31552251, 2019). "Although TDO2 expression was noted in the naïve lung tissues of WT and IDO−/− mice, significantly reduced expression was observed in tumor bearing mice." (PMID 27705910, 2016).
tumor (continued). "In tumor cells, the conversion of tryptophan to kynurenine is primary mediated by two dioxygenases, indoleamine-2,3-dioxygenase (IDO) and tryptophan-2,3-dioxygenase (TDO)." (PMID 25120544, 2014). "Both TDO2 and IDO1 play key roles in the metabolism of Trp, and therefore, it is hypothesized that they play a role in tumor immunity." (PMID 40103267, 2025). "Based on the relevance of high IDO1 and TDO2 expression in many tumours and their poor prognosis, and the role of many products of the KP metabolic in driving tumour development, we believe it is reasonable to explore IDO inhibitors, TDO2 inhibitors and dual IDO1/TDO2 inhibitors." (PMID 40040508, 2025). "IDO1 and TDO2 are the first rate-limiting metalloenzymes that are responsible for the degradation from TRP to kynurenine, which is closely correlated to the failure of anticancer immunotherapies and tumor progression through the activation of AhR." (PMID 41255573, 2025). "However, in the TME, tumor cells, stromal cells, or myeloid-derived suppressor cells (MDSCs) highly express indoleamine 2,3-dioxygenase (IDO1) or tryptophan 2,3-dioxygenase (TDO)." (PMID 41293169, 2025). "Additionally, the TDO2 inhibitor LM10 suppressed the growth of LNCaP-EnzR and PC3 xenograft tumours in vivo." (PMID 40759641, 2025). "Nonetheless, IDO2 expression was closely aligned with AhR expression and tumour cellularity, while no such association was found between AhR and either IDO1 or TDO2." (PMID 40471422, 2025). "TDO2 overexpression has been documented in gliomas, where it drives Trp metabolism to Kyn, activating the AhR and downstream PI3K/AKT signaling pathways to promote tumor stemness and growth." (PMID 41332472, 2025). "Additionally, tryptophan metabolism facilitates immune escape through tumor-intrinsic upregulation of IDO and tryptophan 2,3-dioxygenase (TDO) enzymes." (PMID 41050070, 2025). "Mechanistically, TDO2 upregulates interleukin-8 (IL-8), activating the protein kinase B (AKT)/ glycogen synthase kinase-3 (GSK3β) pathway and promoting M2 macrophage polarization, thereby accelerating tumor progression in EC." (PMID 38462620, 2024). "Therefore, cancer trends showed a high expression of IDO1 and/or TDO2 to catabolize TRY, generating abundant KYN that further activates AHR and its targets for the sake of tumor progression." (PMID 38347841, 2024). "Furthermore, overexpression of miR-126-5p and TDO2 promoted HCCLM3 cells and HepG2 cells proliferation, migration, invasion and in vivo tumor cell xenograft formation and growth." (PMID 35056756, 2022). "Meanwhile, a higher tumorigenic rate of TDO2 overexpression SMC-7721 cells was found in immunodeficient mice, and TDO2 overexpression SMC-7721 revealed strengthened cell proliferation capability and rapid tumor growth in vivo, when compared to the SMC-7721 vector group." (PMID 34657635, 2021). "Interestingly, due to the activation of AHR, tumor cells express high levels of IDO1 and TDO2 to promote plasticity." (PMID 33692337, 2021). "Tryptanthrin and its analogs were shown to be anti-tumor agents both in vitro on cancer cell lines and in vivo on rat model, being potent inhibitors of indoleamine 2,3-dioxygenase (IDO1), tryptophan 2,3-dioxygenase (TDO) and indoleamine 2,3-dioxygenase 2 (IDO2)." (PMID 33374765, 2020). "Finally, we examined the effects of tryptophan 2,3-dioxygenase (TDO2), a Trp-catabolizing enzyme that is expressed in tumor cells and induces immune resistance, on TrpRS-mediated high-affinity Trp uptake." (PMID 33261077, 2020). "It would also be possible that primary UM without TDO2 expression starts expressing TDO in response to a factor in the tumor microenvironment." (PMID 32050636, 2020). "CircZNF566 is a novel tumor promoter in HCC and functions through the circZNF566/ miR-4738-3p /TDO2 axis; in addition, circZNF566 may serve as a novel diagnostic marker, prognostic indicator, and target for the treatment of HCC." (PMID 32532962, 2020).
tumor (continued). "Similarly, tryptophan 2,3-dioxygenase (TDO), which catalyzes the same reaction of IDO1, is expressed in a wide range of malignancies and has been shown to promote tumor progression and metastasis." (PMID 32536910, 2020). "Considering that these subtypes are associated with higher rates of lymph node metastasis, elevation of the early KP enzymes TDO2, KMO and KYNU may promote tumour aggressiveness and metastasis." (PMID 26646699, 2016). "Together, our findings demonstrate that IL4I1+ TAMs and TDO2+ myCAFs synergistically establish an immunosuppressive, ferroptosis-resistant niche via AhR signaling in solid predominant LUAD and offer promising therapeutic strategies to reprogram the tumor microenvironment." (PMID 41431173, 2025). "Notably, IDO2 exhibited a strong association with AhR expression and tumour cell density, with no observed correlation between AhR and either IDO1 or TDO2." (PMID 40471422, 2025). "Tryptophan-2,3-dioxygenase (TDO2) and indoleamine-2,3-dioxygenase (IDO1) are structurally distinct heme enzymes that catalyze the conversion of L-tryptophan to N-formyl-kynurenine, and play important roles in metabolism, inflammation, and tumor immune surveillance." (PMID 39537789, 2024). "Interestingly, combinatorial inhibition of IDO1, IDO2, and TDO2 (together thought to be the predominant rate-limiting enzymes for the kynurenine pathway) did not impact tumor viability in patient derived GBM cells." (PMID 36900311, 2023). "Using mRNA from diffuse and intestinal GC tumor samples of a Western cohort, this study reports the expression level of the immunomodulatory aryl-hydrocarbon receptor (AhR), and genes involved in immune suppression (PD1, PD-L1, PD-L2) and the early steps of tryptophan metabolism (IDO1, IDO2, TDO2)." (PMID 35203450, 2022). "This suggests that the presence of CD8+ T-cell infiltration in tumor is very strongly correlated with IDO-1 expression, strongly correlated with IDO-2 expression, but not so strongly correlated with TDO-2 expression." (PMID 34367262, 2021). "However, the addition of Kyn diminished the inhibitory effect of LM10 on LNCaP-EnzR xenograft tumour growth in vivo but not that of CH223191, suggesting that Kyn participates in mediating the growth of TDO2-promoted recurrent CRPC in vivo." (PMID 40759641, 2025). "Not all cancers exhibit high levels of IDO1 or TDO2 expression, and the effectiveness of KYN pathway inhibitors may vary depending on tumor type and microenvironment." (PMID 39997327, 2025). "In contrast, in the present study, through scRNA-Seq, we found that TDO2 was specifically and highly expressed in a subgroup of myofibroblasts (TDO2+ myofibroblasts) in OSCC, whereas TDO2 expression was absent on tumor cells according to scRNA-Seq analysis and mIHC staining." (PMID 35972800, 2022).
cancer (109 papers, 2016 to 2026). A tumor composed of atypical neoplastic, often pleomorphic cells that invade other tissues. "TDO2 (TDO gene) expression has been associated with the cancer stage, presence of immune infiltrates, disease aggressiveness, poor OS and DFS, and clinical outcomes in TNBC." (PMID 39735530, 2024). "The authors also noted that overexpressing TDO2 in cancer cell lines was associated with increases in migration and invasion; TDO2-specific siRNA knockdown had the opposite effect." (PMID 39272943, 2024). "Overexpression of TDO2 is involved in anoikis resistance, spheroid formation, proliferation, and invasion and is associated with poor prognosis in a variety of cancers such as breast, esophagus, colon, and rectal cancer." (PMID 34174844, 2021). "TDO2 is expressed predominantly in the central nervous system in normal tissue but is overexpressed in various cancers and linked to promotion of survival and immune resistance." (PMID 33889302, 2021). "Taken together, these data suggest that in primary UM, TDO2 RNA expression is generally low (compared to other cancers), but the increased TDO2 RNA expression is associated with the poor prognosis markers, BAP1 mutations, and M3." (PMID 32050636, 2020). "IDO1 and TDO2 expression are associated with numerous tolerogenic immune cells, including suppression of effector T cells and infiltration of MDSCs and Tregs in multiple cancer types." (PMID 38339226, 2024). "However, TDO2 expression in different cancer types (notably gliomas) is associated with tumor immune resistance." (PMID 37196768, 2023). "In addition, Gal-1 secreted by cancer cells can induce cancer-associated fibroblasts to activate TDO2-ATK signaling and produce the tryptophan metabolite kynurenine, which reportedly can induce T cell apoptosis." (PMID 34572346, 2021). "In addition, we recently identified the L-amino acid oxidase interleukin-4-induced-1 (IL4I1) as a novel and very potent upstream regulator of AHR, and we showed that IL4I1 associates more frequently with AHR activity than IDO1 or TDO2 in cancer." (PMID 33920868, 2021). "In particular, enzymes involved in the kynurenine pathway—such as IDO and tryptophan 2,3-dioxygenase (TDO)—have been correlated with poor prognosis in multiple cancer types." (PMID 40666095, 2025). "Indoleamine 2,3-dioxygenase (IDO) and tryptophan 2,3-dioxygenase (TDO) are overexpressed in various cancers and catalyze tryptophan degradation to KYN, which is further converted to KYNA by KYN aminotransferases." (PMID 41459506, 2025). "Several enzymes involved in the KYN pathway, including indoleamine 2,3-dioxygenase 1 (IDO1) and tryptophan 2,3-dioxygenase (TDO2), are upregulated in cancer cells and contribute to therapy resistance." (PMID 39997327, 2025). "Upregulation of tryptophan catabolism by IDO1 and TDO2 is a well-described mechanism of cancer immune evasion." (PMID 38339226, 2024). "High levels of IDO and tryptophan 2,3-dioxygenase (TDO) in cancer inhibit the cancer-killing effects of T cells by reducing tryptophan levels in TME." (PMID 38238756, 2024). "In a phase I clinical trial evaluating a dual IDO1/TDO2 inhibitor in a small cohort of patients with various cancer types, treatment was well tolerated to the point that a MTD was not determined." (PMID 38451784, 2024). "IDO1 and TDO2 are the initial Trp metabolizing enzymes of KP and are highly expressed in a variety of cancers." (PMID 38887298, 2024). "Enzymes, such as indoleamine-2,3-dioxygenase 1 (IDO1), IDO2, or tryptophan-2,3-dioxygenase, catalyze this, thereby modulating immunity and fostering cancer progression via tryptophan depletion and aryl hydrocarbon receptor activation." (PMID 38732512, 2024). "Both IDO1 and TDO2 are responsible for the conversion of Trp to Kyn that block anti-cancer activity of cytotoxic T cells within TME." (PMID 39769192, 2024).
cancer (continued). "IDO1/TDO2 are aberrantly expressed in carcinomas and metabolize TRP into the immune-suppressive metabolite kynurenine (KYN), which can engage the aryl hydrocarbon receptor to drive immunosuppressive transcriptional programs." (PMID 38451784, 2024). "In the context of CRC, deficiency in adenomatous polyposis coli (APC) results in TCF4/β-catenin-mediated upregulation of the TDO2-Kyn-AhR axis to increase glycolysis and drive anabolic cancer cell growth." (PMID 37876966, 2023). "Blocking IDO1/TDO2 inhibited the colony-forming ability only in CR cell models, further demonstrating altered metabolism via the dependence of CR cancer cells on these enzymes for survival." (PMID 37226257, 2023). "As a result, the overexpression of the tryptophan‐degrading enzymes such as indoleamine 2,3‐dioxygenase (IDO) and tryptophan 2,3‐dioxygenase (TDO) in cancer has led to extended research on the tryptophan–kynurenine pathway in cancer." (PMID 37644823, 2023). "Currently, selective IDO1/TDO2 inhibitors are being evaluated at different clinical phases to treat various cancers such as epacadostat, navoximod, BMS-986205, and PF-06840003." (PMID 37241719, 2023). "Our results showed that TDO2 expression is associated with TMB in 10 different types of cancer and with MSI in 9 different types of cancer." (PMID 36118672, 2022). "Tryptophan (Trp) is converted to Kynurenine (Kyn) after catalysis via 2,3-dioxygenase 1 (IDO1), IDO2, and tryptophan-2,3-dioxygenase (TDO) in several cancers." (PMID 35956752, 2022). "QPRT is also expressed in 4/28 cancers, all in association with expression of TDO2 and FAMID and 1 with IDO, and in other cancer types." (PMID 36286592, 2022). "Of the 10 IDO1 expressing cancers, only 6 co-express TDO2, 3 co-express FAMID and 4 co-express each of the two Trp transporters, with ratios of 60%, 30%, 40% and 40% respectively." (PMID 36286592, 2022). "Only 6 cancers were associated with expression of IDO2, 5 of which were associated with expression of the 2 Trp transporters, IDO1 and TDO2, and 2 with FAMID." (PMID 36286592, 2022). "To shed more light on the role of TDO2 in human cancer, we explored the expression profiles of TDO2 and identified its prognostic value in pancancer analysis through TCGA, CCLE, and GTEx databases." (PMID 36118672, 2022). "We further investigated the correlation between IDO1 and TDO2 expressions and T cell infiltration markers in other types of human cancer, ranked by their immunogenicity." (PMID 35780226, 2022). "Subsequently, we employed coexpression analysis of TDO2 with immune cells infiltration, immune checkpoint-related genes MMR, DNMT, TMB, and MSI to elucidate the biological functions of TDO2 across 33 types of cancers." (PMID 36118672, 2022). "It has been confirmed that TDO2 is involved in mediating tumoral immune resistance, which raised considerable interest of targeting TDO2 for cancer immunotherapy." (PMID 36118672, 2022). "According to our results, DNMTs and TDO2 expression were specifically correlated in numerous types of cancer, indicating DNA methylation is likely to function in modulating TDO2." (PMID 36118672, 2022). "Our findings revealed that TDO2 expression highly correlates with the MMR genes expression in different cancer types (KIRP, LGG, PAAD, and PRAD)." (PMID 36118672, 2022). "We searched the PubMed, Cochrane Library, and Web of Science databases to find publications concerning TDO2 expression in malignant tumor patients up to June 2021." (PMID 36263228, 2022). "Upregulation of indoleamine-2,3-dioxygenase 1 (IDO1) and tryptophan-2,3-dioxygenase 2 (TDO2) by cancer cells result in the tryptophan degradation into kynurenine." (PMID 35250965, 2021). "We also explored the biofunctional roles of TDO2 in progression, cancer stemness, and drug resistance using BC cell lines with RNA interference (RNAi) knockdown and forced expression of TDO2." (PMID 34101386, 2021).